PRNP (prion protein (Kanno blood group))
Diseases named in the same sentence as PRNP in open-access papers (continued):
Sharing a sentence is not in itself a finding about the gene and the disease.
cancer (continued). "Subsequently, we aimed to understand how PRNP expression correlates with the levels of other genes expressed by cancer cells." (PMID 38347462, 2024). "The levels of PRNP mRNA expression in 26 distinct types of cancer were initially examined to assess the significance of PRNP in malignancies." (PMID 39170916, 2024). "In particular, bladder, head and neck, kidney, and lung tumors were the cancer types with the highest number of positive correlations between PRNP expression and vesicle dynamics signatures among distinct tumor stages." (PMID 38347462, 2024). "Recently, remarkable studies have affirmed a high expression of PRNP(PrPC) in different types of cancers, consistent with our findings." (PMID 39170916, 2024). "The TIMER2.0 database was utilized to further evaluate the pan-cancer data for the expression of PRNP and macrophages." (PMID 37535656, 2023). "The findings of Antonacopoulou's study shed light on the higher expression of POLR2F and PRNP in carcinomas compared to normal tissue samples, indicating a possible role in colorectal cancer." (PMID 37884559, 2023). "Aberrant expression of PRNP has been observed in many types of cancer, including cancers of the digestive system melanoma and oral squamous cell carcinoma." (PMID 36213323, 2022). "PRNP was significantly correlated with cancer stages, primary therapy outcomes, and age in OC patients." (PMID 36213323, 2022). "This intriguing difference suggested the probably multiple and complicated regulatory mechanisms of PRNP for various types of cancer." (PMID 36213323, 2022). "Our finding that ER stress can up-regulate PRNP gene expression has certain implications in cancer because cancers are ER stressed and PrP has been reported to have protective functions that appear to be involved in the resistance of cancers to chemotherapy." (PMID 23497519, 2013). "To determine if PRNP gene expression in the basal carcinoma cell lines depends on ER stress, we knocked down (KD) ATF6α and XBP1 with siRNAs in the MDA-MB-231 and HS578T cell lines." (PMID 23497519, 2013). "PRNP is a gene encoding the prion protein PrP, which has been noted for its role in the nervous system and is known to be upregulated in various cancers and associated with both cell proliferation and metastasis." (PMID 35804944, 2022). "This suggests the potential of PRNP as a therapeutic target for cancer treatment." (PMID 35804944, 2022). "Further investigation is required to ascertain the functions of PRNP and its isoforms in cancer." (PMID 36432484, 2022). "In addition, previous studies have been reported that cancer tissues showed more genetic instability and elevated expression of the PRNP gene." (PMID 32560489, 2020). "Although the roles of PRNP in several cancers have been investigated, no pan-cancer analysis has revealed its relationship with tumorigenesis and immunity." (PMID 39170916, 2024). "Up to now, we have not found any published paper exploring the role of PRNP in OC through the regulation of ferroptosis, while there were evidences of PRNP acting as an oncogene in other cancer types." (PMID 36213323, 2022). "While the overexpression of PrP definitely has a negative impact on several types of cancers, surprisingly little is known about the regulation of PRNP gene expression." (PMID 23497519, 2013).
tumor (58 papers, 2007 to 2025). "Altogether these data show that β-catenin/TCF4 bind Wnt-responsive element (WRE)-encompassing enhancers specifically active in PRNP in human β-catenin activated tumor cells." (PMID 38589873, 2024). "Single-cell analysis showed that PRNP was highly expressed in M1 phenotype macrophages, essential tumor-suppressing cells in the tumor stroma." (PMID 37535656, 2023). "Fyn and specificity protein 1 (SP1) played a significant role in the reduced expression of SATB1 and tumor progression in CRC following PRNP knockdown." (PMID 36359353, 2022). "Aside from PRNP, other members of the prion gene family were found to be up-regulated in various tumor tissues and cancer cell lines." (PMID 33418999, 2021). "More precisely, we uncovered that expression of the PrPC-encoding gene PRNP, which is enriched in CMS4 tumours, is associated with a YAP/TAZ signature in CRC patients and cell lines." (PMID 33126419, 2020). "Many human tumor samples also gained expression of a coordinately regulated module associated with advanced malignancy (ABCC1, FOXO3A, LIF, PIK3R1, PRNP, TNC, TIMP3 and VEGF)." (PMID 17615082, 2007). "Through the Cancer Genome Atlas (TCGA), Gene Expression Omnibus (GEO) and Clinical Proteome Tumor Analysis Consortium (CPTAC) databases, this study explored the expression and diagnostic value of PRNP between OSCC and normal tissues from mRNA and protein levels." (PMID 38370370, 2024). "Then, we analyzed PRNP+ and PRNP- GBM cells profiled by single-cell RNA-seq to further understand the molecular context within which PRNP/PrPC might function in this tumor." (PMID 38347462, 2024). "Tumor immune cell infiltration analysis and clinical validation revealed that PRNP (Prion protein), SNCA (Synuclein alpha), and COX17 (Cytochrome c oxidase copper chaperone COX17) may be closely correlated with immune cell infiltration and ICG expression." (PMID 37153542, 2023). "It is tempting to speculate that host, genetic, or immunological factors outside of the PRNP open reading frame that contributed to the development of neoplasia might have had a suppressive effect on PrPSc accumulation." (PMID 35318913, 2022). "In general, this study demonstrated for the first time that ferroptosis-related gene PRNP exerted a tumor-suppressive role in OC and the aberrant expression and function of PRNP making it a potential novel biomarker for OC diagnosis, prognosis, and response to immunotherapies." (PMID 36213323, 2022). "These accordance findings of PRNP in aspects of expression and survival in OC make us focused on PRNP and assume that PRNP might become a promising tumor-suppressive biomarker as well as a molecular target for further investigations." (PMID 36213323, 2022). "This study demonstrated for the first time showed that ferroptosis-related gene PRNP exerted a tumor suppressive role in OC and the aberrant expression and function of PRNP making it a potential novel biomarker for OC diagnosis, prognosis, and response to immunotherapies." (PMID 36213323, 2022). "Similarly, combining PRNP silencing with fucoidan provides an enhanced efficacy against colorectal CSCs’ proliferation and migration in vitro, while reducing tumor volume and angiogenesis in vivo." (PMID 31618844, 2019). "In addition, mechanistically, direct binding of PRNP to filamin A may exert the oncogenic role to promote the aggressiveness of tumor cells, and prognostic value to predict poor clinical outcome of digestive cancer has been issued." (PMID 36213323, 2022). "Thus, we hypothesize that direct interactions of miR-148a with ITGA5 and PRNP play an important role in tumor progression and metastasis." (PMID 34135940, 2021). "In addition, taking into account that PRNP was identified as a ferroptosis-related gene in our study, it was rational to speculate that the tumor-inhibitory role of PRNP in OC patients might partially be through ferroptosis in a way dependent on Ras-MEK-ERK signaling pathway." (PMID 36213323, 2022).
tumor (continued). "Among the top dysregulated genes when comparing control and tumor free tissue were those involved in apoptosis (CIDEC, MUC1, ZBTB16, PRNP, ECT2), immune response (IFI27) and differentiation (KRT36)." (PMID 28038473, 2017). "Next, in vitro experiments showed that PRNP overexpression decreased the proliferation capacity of two OC cell lines suggesting, unlike other types of solid tumor, a potential tumor-suppressive role of PNRP." (PMID 37452879, 2023). "Additionally we selected seven other genes, ATF3, ADAMTS1, EGFR, PRNP, IGFBP6, ID4 and FN1, found to be differentially expressed according to tumor subtype and ER+/ER- classification from the tumor-specific differentially expressed gene-set." (PMID 19116033, 2008).
neurological diseases (25 papers, 2009 to 2025). "Though primarily studied in neurological disorders, the functional annotation analysis of PRNP showed potential roles that might have a role in RA." (PMID 41021591, 2025). "Although the direct link of PRNP to RA is underexplored, its role in oxidative stress and neurological disorders may suggest a potential cross-talk between immune and neuronal pathways." (PMID 41021591, 2025).
infectious disease (13 papers, 2007 to 2025). A disorder directly resulting from the presence and activity of a microbial, viral, or parasitic agent in humans. "Fitness variation associated with the cervid PRNP gene provides a valuable opportunity to investigate the role of infectious disease on selection in a natural system." (PMID 34430048, 2021). "Continuous monitoring and reporting of WTD PRNP polymorphism might prove to be an important tool to wildlife and regulatory bodies in handling the increasing threat of CWD, as well as deepening the understanding of their role in infectious disease dynamics." (PMID 40872835, 2025).
genetic disease (5 papers, 2013 to 2022). "Cardiomyopathy is a co-morbidity of some prion diseases including genetic disease caused by mutations within the PrP gene (PRNP)." (PMID 36138047, 2022). "The massive sequencing approach based on NGS platforms has become the first tier for molecular diagnosis of heterogeneous genetic disorders such as AD and FTD, integrated with PCR analyses of the C9orf72 hexanucleotide repeat expansion and the PRNP octapeptide repeat region." (PMID 33203472, 2020).
brain disease (4 papers, 2018 to 2023). "(A temporary exhibit in another museum building, Cannibals: Myth and Reality, included mention of mutation in the section on the PRNP gene; one variant allele provides protection from “a fatal brain disease” [i.e., kuru])." (PMID 36945662, 2023).
peripheral neuropathy (3 papers, 2017 to 2022). A disorder affecting the peripheral nervous system. "In this report we present a genetic case of prion disease with an unusual peripheral neuropathy phenotype and two variants in the PRNP gene." (PMID 31953922, 2020). "However, approximately 28.4% of sporadic CJD cases have symptoms suggestive of peripheral neuropathy and some PRNP variants have been seen in patients with autonomic neuropathy." (PMID 31953922, 2020).
inflammation (1 paper, 2014). Aberrant reaction of the microcirculation characterized by movement of fluid and leukocytes from the blood into extravascular tissues. "Induction of plasma membrane PRNP suggested that PRNP interact with many other proteins and induced vascular inflammation." (PMID 24993133, 2014).
movement disorder (1 paper, 2022). Neurological conditions resulting in abnormal voluntary or involuntary movement, which may impact the speed, fluency, quality and ease of movement. "Disease severity and PRNP codon 129 polymorphism were associated with different movement disorder phenotypes." (PMID 35841311, 2022). "We performed an analysis to identify whether there were patterns of movement disorders associated with disease aetiology, PRNP codon 129 polymorphism, disease severity rating scales, magnetic resonance imaging (MRI) and cerebrospinal fluid (CSF) findings." (PMID 35841311, 2022).
PRNP also shares sentences with these, for which no sentence is quoted: Stroke (13 papers); memory impairment (12); pancreatic ductal adenocarcinoma (11); Cerebral ischemia (10); Parkinson’s (9); synucleinopathies (8); ischemia (7); schwannoma (7); proteinopathies (6); Anxiety (5); brain injury (5); insomnia (5); osteosarcoma (5); brain tumors (4); chronic kidney disease (4); iron deficiency (4); ischemic disease (4); prostate carcinoma (4); type 2 diabetes (4); bacterial infection (3); colorectal adenocarcinoma (3); colorectal tumors (3); endometrial carcinoma (3); epilepsy (3); familial Creutzfeldt-Jakob disease (3); hepatocellular carcinoma (3); Huntington disease-like 1 (3); ischemic stroke (3); adenocarcinoma (2); anemia (2).
A further 137 diseases each share a sentence with PRNP in 2 papers or fewer.